CXCR3 (C-X-C motif chemokine receptor 3)
Diseases named in the same sentence as CXCR3 in open-access papers (continued):
Sharing a sentence is not in itself a finding about the gene and the disease.
tumor (continued). "This, in concert with anti-PD-1 ICB, significantly increases tumor infiltration by lymphocytes likely through CXCL9 engagement with its cognate receptor expressed by these cells-CXC motif chemokine receptor 3 (CXCR3)." (PMID 38014191, 2023). "CXCL9 and CXCL10 through their receptor CXCR3 regulate immune cell migration, differentiation, and activation, leading to tumor suppression under some conditions." (PMID 37296899, 2023). "Animals exposed to the CXCR3 antagonist indeed had slower tumor growth than control animals with an intact CXCR3 chemokine axis, supporting the conclusion that antagonism of CXCR3 inhibits tumor growth." (PMID 37686653, 2023). "Here, we show that the spleen is a critical site harboring tumor-specific CD8 T cells that functionally segregate based on differential Cxcr3 and Klrg1 expression." (PMID 36472588, 2023). "CXCR3 is known to have a key role in T-cell trafficking to inflammatory sites and is required for immune cell trafficking to tumor tissues." (PMID 37895310, 2023). "Previous studies have shown that chemokines CXCL9 and CXCL10 can recruit CD8+ T cells, Th1 cells and NK cells by recognizing CXCR3 signals, thus triggering anti-tumor response." (PMID 37950246, 2023). "High expression of CXCR3 and CXCL9/10 has been associated with a poor prognosis, tumor growth, and increased risk of metastasis." (PMID 36180422, 2022). "For example, tumor CXCR3 and tumor-draining lymph node CXCL9 and CXCL10 promote the metastasis of murine melanoma cell line B16F10." (PMID 35216243, 2022). "It is already known that CXCR3 is primarily expressed on vascular cells, NK cells, tumor cells, and activated T lymphocytes and binds to CXCL9 to CXCL11." (PMID 35978426, 2022). "Several studies have shown that CXCR3 and its ligands modulate the tumor microenvironment in a pro- or anti-tumorigenic manner." (PMID 35897689, 2022). "When these molecules are highly produced within the tumor, their ligation with CXCR3 allows their migration into tumors." (PMID 36429101, 2022). "High level of CXCL10 in tumor tissues attracts CXCR3+ Th1 and CD8+ T cells to inflamed tumor sites and stimulates T-cell polarization into effector T cells to promote killing of cancer cells." (PMID 35207629, 2022). "CXCR3, on the other hand, regulates metastasis through impairment of host anti-tumor immunity due to suppression of IFN-γ production and T cell expansion." (PMID 35910801, 2022). "Meanwhile, one investigator found in a mouse model that CXCL9 expressed by tumor cells suppressed local tumor growth and metastasis by recruiting host NK cells and a large number of CXCR3+CD4+ and CXCR3+CD8+ host T cells." (PMID 36479091, 2022). "We further reveal that the CXCL10/CXCR3 signaling of tumor cells is augmented via an autocrine pathway." (PMID 36612121, 2022). "This discovery indicates a positive correlation between CXCR3 pathway activation and anti-tumor immunity." (PMID 35562800, 2022). "The previous study by Chow and the CXCR3 blocking experiment in the study by Han both confirmed that the anti-tumor effect of PD-1 blockade therapy was significantly weaken after the loss of CXCR3 signaling." (PMID 36479091, 2022). "Tumor-associated dendritic cells can produce high levels of CXCL9, which promotes tumor progression by increasing programmed death-ligand 1 (PD-L1) expression through the activation of CXCR3-related signals." (PMID 36504808, 2022). "A variety of chemokine/chemokine receptor strategies have been utilised in immunotherapeutic T cell preclinical work to facilitate CAR T cell targeting to tumour masses, including the exploiting the CXCR3, CXCR2, CCR5, CCR2, and CCR3 axes." (PMID 35205725, 2022). "The characteristics and roles of the CXCR3 chemokine system make it a potential target for immunotherapy and offer new hope for tumor treatment." (PMID 36479091, 2022).
tumor (continued). "For the study of CXCR3 and its ligands, in recent years, many studies have verified that the expression of CXCR3 and its ligands in the body is closely related to tumor immunity, tumorigenesis, and metastasis." (PMID 36479091, 2022). "Anti-CXCR3 treatment completely abrogated the attenuated tumor growth observed in GPR182−/− mice, suggesting that the improved anti-tumor immunity seen in GPR182−/− mice is dependent on the CXCL9/CXCL10/CXCR3 axis." (PMID 35013216, 2022). "CXCR3 plays a dual role in affecting tumor progression and the microenvironment, and its effects vary when immunotherapy is used against different tumors." (PMID 36479091, 2022). "In humans, CXCR3 exists in the functional splice variants, CXCR3A and CXCR3B, which either have pro- or anti-tumor activity, respectively." (PMID 36539774, 2022). "The chemokine CXCL9, along with its two family members CXCL10 and CXCL11, promotes tumour-suppressive lymphocytic infiltration in solid tumours via its receptor CXCR3." (PMID 35314795, 2022). "This article reviews the significance and mechanism of action of the chemokine receptor CXCR3 and its specific ligands in tumor development." (PMID 36479091, 2022). "CXCL9 can bind to CXCR3 expressed in tumor cells to recruit CD4 + T cells, thus promoting the production of CCL5 in TME, promoting tumor invasion." (PMID 36159780, 2022). "IFN-γ promoted the accumulation of CXCR3+ lymphocytes in tumor tissues, which exhibited anti-tumor immune properties." (PMID 35865015, 2022). "Further study needs to be done to explore the tumor heterogeneity’s impact on CXCR3 pathway activation levels." (PMID 35562800, 2022). "CXCL10, in addition to inducing effector Th1 cells, also recruits CXCR3+CD8+ T cells to tumor sites and induces granzyme-b production through these cells, thereby enhancing the anti-tumor effect." (PMID 36479091, 2022). "These chemokines promote low cytotoxic CD56+ NK recruitment by binding to CXCR3, ultimately leading to tumor escape." (PMID 36479091, 2022). "CXCR3 is expressed and secreted by tumor epithelial, inflammatory, and endothelial cells in the TME." (PMID 36479091, 2022). "For instance, DCs secrete CXCL9 and CXCL10 as chemoattractors for recruiting CXCR3+ T cells into the tumor microenvironment." (PMID 35347124, 2022). "In advanced‐stage CRC, Th17 inhibits migration of CTLs in tumor tissues by downregulating the expression of CXCR3 via the IL‐17A/STAT3 axis." (PMID 35791509, 2022). "CXCR3 blockade reverses the improved anti-tumor immunity and T-cell infiltration characteristics in GPR182-deficient mice." (PMID 36479091, 2022). "Suppression of tumour growth was associated with a reduced expression of immune checkpoint molecules, PD-1, TIGIT and LAG-3 with upregulation of CXCR3 expression." (PMID 36104795, 2022). "While orthotopic implantation of 3LL led to the recruitment of migratory NK cells in tumor-bearing lungs in a CXCR3-dependent manner, the control of lung-inoculated 3LL cells was mediated by lung-resident NK cells." (PMID 36733396, 2022). "The tumor core analysis demonstrated an immune desert with few immune cell infiltration, mainly CXCR3+ CD4+ cells, suggesting a new role for CXCR3 that grants access to CD4+ cells." (PMID 36050391, 2022). "Nevertheless, this study offered a crucial finding that an increase in CXCR3 expression significantly promotes tumor infiltration of TAMs and M2 polarization in neuroendocrine differentiated CRC in vivo and vitro." (PMID 36030223, 2022). "Following our earlier observations of elevated CXCL11 and CCL20 transcripts in the tumor epithelial compartment, we observed a positive correlation with the expression of their respective receptors, CXCR3 and CCR6, in the microenvironment." (PMID 35394843, 2022). "The differential expression of CXCR3 in many tumor tissues determines the inhibition or promotion of tumor growth." (PMID 36479091, 2022).
tumor (continued). "It positively affects the anti-tumor immune response of CXCR3-expressing CD8+ T lymphocytes, Th1 cells, cytotoxic T lymphocytes, and NK cells." (PMID 36479091, 2022). "CXCR3 chemokine expression by tumor cells, macrophages, and cDCs plays essential roles in different systems." (PMID 36479091, 2022). "We sorted TDO2+ and TDO2– myofibroblasts from tumor tissues to perform coculture experiments with CXCR3+CD3+ T cells on imaging plates." (PMID 35972800, 2022). "Further research into the relevance of CXCR3 isoforms relative to the inflammatory tumor milieu for the response to chemotherapy is needed to elucidate the role of the immune system in the response to chemotherapy in MIBC." (PMID 35027623, 2022). "In lung and renal cell carcinoma models, intratumoral injection of CXCL9 or CXCL10 proteins, respectively, reduced neovascularization and delayed tumor growth by inducing tumor‐infiltrating CXCR3+ monocytes." (PMID 35702353, 2022). "CXCL9 and CXCL10 are chemokine ligands of CXCR3, which differ from other chemokines due to their ability to restrain tumor growth and enhance antitumor immunity." (PMID 35320940, 2022). "Changes in CXCR3+ CD8+ T cell tumor trafficking and activation status that correlated with response were suggested as possible mechanisms for the observed increase in clinical activity." (PMID 36106641, 2022). "Investigators have recently demonstrated that replenishing the gut microbiome with Akkermansia muciniphila in germ-free mice receiving FMTs from patients responding to immunotherapy promotes CCR9 + CXCR3 + CD4 + T-lymphocyte migration into tumor beds." (PMID 35073876, 2022). "On the one hand, CXCR3 and its ligands can inhibit tumor growth by activating immune effector cells; on the other hand, CXCR3 exhibits a role in promoting tumor growth and metastasis in some tumors." (PMID 36479091, 2022). "(A–D) The treated (right side) and untreated tumors (left side) were harvested at the end of the experiment and analyzed for the CD8+/CD4+ ratio (A) and the frequency of CD8+ (B), CD8+ CXCR4+ (C), and CD8+ CXCR3+ (D) in the tumor microenvironment (TME)." (PMID 35314027, 2022). "Accordingly, patients with advanced tumor stage have higher CXCR3 scores in ICI cohort (Kruskal–Wallis test, p < 0.001)." (PMID 35562800, 2022). "CXCR3B inhibits the cAMP/PKA signaling pathway to reduce cell migration, and CXCR3 activates the PLC-B/Ca2+ pathway to promote tumor cell dissemination and metastasis, so high expression of CXCR3B suggests a good prognosis." (PMID 36479091, 2022). "CXCL9, CXCL10, and CXCL11/CXCR3 axes can induce immune activation and then inhibit tumor growth, which are potential novel therapeutic targets for cancer therapy." (PMID 36090326, 2022). "The anti-tumor effect of CXCR3 has been demonstrated by its ability to activate the autoimmune system response to achieve anti-tumor growth." (PMID 36479091, 2022). "Pharmacological antagonism of AMG487 against CXCR3 was effective in inhibiting the proliferation of osteosarcoma and colon cancer cells in vitro and attenuated lung metastasis in mouse tumor models." (PMID 35702353, 2022). "When mice received FMT from donor responders, they exhibited decreased tumour size, increased accumulation of CD4+CXCR3+ tumour infiltrating lymphocytes (TILs), and increased expression of PD-L1 on splenic CD4+ cells." (PMID 35565229, 2022). "Neutralizing CXCL9, CXCL10, or IFN-γ reduces CXCR3-expressing activated T cells infiltrating tumors and abrogates IL-7/IL-7rα-Fc-mediated tumor growth inhibition." (PMID 36479091, 2022). "As CXCR3 chemokines are thought to contribute to tumour-suppressive lymphocytic infiltration, we next quantified different intratumoral immune cell subsets by digital analysis of immunohistochemically stained mesenteric tumour tissues." (PMID 35314795, 2022). "The related role of the CXCR3 ligand is also being explored, and changes in CXCR3 ligand recognition in vivo can fine-tune the effect of CXCR3 anti-tumor activity." (PMID 36479091, 2022).
tumor (continued). "Expression of CXCL10 upon encounter of tumor antigens in a synthetic notch receptor (synNotch) steered manner improved subsequent CXCR3-based tumor infiltration by CAR T cells." (PMID 36366354, 2022). "For example, CXCR3 is expressed on activated NK cells and functions to enhance NK cell cytotoxicity and promote NK cell proliferation and homing to tumor sites, through binding to its ligands." (PMID 36741396, 2022). "Comparing top DEGs which differentiate dura-originating from tumor-originating T cells, dura T cells’ DEGs were related to T cell migration and function, such as CXCR3 and ITGAL, as well as cell motility genes SUSD3 and FGD3." (PMID 35534852, 2022). "The secreted CXCL9 and CXCL10 bind to CXCR3 on the surface of a subpopulation of breast tumour cells, which promotes initiation and growth of metastatic tumour cells." (PMID 35869057, 2022). "CXCR3 promoted T-cell migration to the tumor core, and its mediated CXCR3-CXCL10 signaling pathway drove ccRCC metastasis." (PMID 35677048, 2022). "According to CXCR3 analysis, CXCR3 expression was significantly higher in tumor samples than in normal samples." (PMID 35847936, 2022). "Compounds that enhance the expression of CXCL9, CXCL10 or CXCL11 and decrease the expression of CXCR3 on tumor cells have displayed anti-tumor activity." (PMID 35154121, 2022). "It is known that chemokine receptor CXCR3 and its ligands have an impact on the inflammatory tumor microenvironment by recruiting different immune cell subpopulations." (PMID 35897689, 2022). "IFNγ promoted CXCL10 secretion by myeloid cells in the tumor and, as a result, attracted more CXCR3 expressing effector T cells." (PMID 35270020, 2022). "In this context, CXCL10 was shown to contribute to the therapeutic success of this treatment by promoting the recruitment of CXCR3+CD8+ T cells at the tumor site." (PMID 36429101, 2022). "Attesting to the functional relevance of these effects, measurement of tumor growth by luminescence revealed that Cxcr3–/– mice had increased tumor growth as compared with WT mice." (PMID 35503658, 2022). "Drugs that enhance the expression of paracrine CXCL9, ‐10, and ‐11 and inactivate CXCR3 expression on cancer cells have exhibited antitumor activity in several tumor models." (PMID 35702353, 2022). "The CXCL9,10,11/CXCR3 signaling pathways in the TME mainly facilitate the chemotactic movement of CXCR3-activated immune cells to the tumor site for anti-tumor immunity." (PMID 36479091, 2022). "CCR4, CCR8, CCR10, and CXCR3 induce Treg cell migration to the tumor microenvironment in response to CC and CXC chemokines: CCR4 is bound by CCL17 and CCL22, CCR8 is bound by CCL1, CCR10 is bound by CCL28,and CXCR3 is activated by CXCL9/10/11." (PMID 36012113, 2022). "In HNSCC, CXCR3 was reported to mediate a cross-talk between lymphatic endothelial cells and HNSCC, also showing a positive correlation between CXCR3 expression and lymphovascular tumor invasion." (PMID 36157879, 2022). "Flow cytometry analysis of tumor-infiltrating cells demonstrated that cefepime increased dendritic cells, CXCR3+ CD8+ T cells (consistent with TH1-polarized immunity), and IFNγ+ NK cells, whereas rabusertib alone did not." (PMID 35563520, 2022). "CXCL9, CXCL10, and CXCL11/CXCR3 are anti-tumor angiogenic factors, and the inhibition of tumor angiogenesis can be achieved via upregulating the expression of CXCL9, CXCL10, and CXCL11." (PMID 35770088, 2022). "CXCR3 and its corresponding ligands CXCL9 and CXCL10 are elevated in CRC and associated with tumor metastasis." (PMID 35791509, 2022). "The CXCL10/CXCR3 signaling pathway regulates leukocyte trafficking and angiogenesis through paracrine interactions between tumor and stromal cells." (PMID 35847936, 2022). "In general, ELR+ CXCLs/CXCR1/2 signaling promotes tumor progression while ELR- CXCLs/CXCR3-7 signaling mainly has tumor-suppressive effects." (PMID 36612163, 2022).
tumor (continued). "Gene Set Enrichment Analysis (GSEA) was used to detect crosstalk between the CXCR3 pathway and other signaling pathways to influence the tumor microenvironment." (PMID 35562800, 2022). "In humans, CXCR3 exists in the splice variants, CXCR3A, CXCR3B, and CXCR3alt, which have partly adverse effects on tumor progression." (PMID 36539774, 2022). "We noticed that patients in the two cohorts with higher levels of CXCR3 pathway activation had higher tumor neoantigen burdens (p < 0.05)." (PMID 35562800, 2022). "In solid tumours, CXCL9, along with the other CXCR3 chemokines, has been made responsible for this tumour-suppressive lymphocytic infiltration." (PMID 35314795, 2022). "Results demonstrated that CXCR6 had more effective anti‐tumour responses with prolonged tumour rejection occurring in 33.3% of mice, whereas mice treated with CXCR3 or CCR4 had only 16.7%–0% prolonged tumour rejection." (PMID 36495108, 2022). "It has been acknowledged so far that the CXCR3/ligand signaling axis modulates pro- or anti-tumorigenic features of tumor and endothelial cells." (PMID 35897689, 2022). "We also found statistically significant differences in the expression of PDL-1 in tumor cells (TC) and immune cells (IC) between groups with different CXCR3 pathway activation levels (Kruskal–Wallis test, p < 0.001)." (PMID 35562800, 2022). "However, in contrast to its ligands, CXCL9, CXCL10, and CXCL11, the protein expression of the CXCR3 chemokine receptor protein in colon cancer tissue could be associated with increased tumor size, the occurrence of lymph node or distant metastasis, and poor survival." (PMID 36428508, 2022). "The expression of CXCR3 ligands by the tumour, the elevated serum levels of CXCR3 ligands, or CXCR3 on T cells enhances T cell recruitment and positive clinical outcomes in a range of cancers." (PMID 35205725, 2022). "To elucidate the effect of the CXCR3 pathway on tumor immunogenicity, we compared differences in TNB, TMB, and DDR-related pathway mutation status between the CXCR3-high and CXCR3-low groups." (PMID 35562800, 2022). "CXCL9, 10, and 11 and CXCR3 pathways have two modes of action: immune-activated secretory signaling and tumor cell-derived proliferative metastatic signaling." (PMID 36479091, 2022). "The CXCR3 axis is critical pathway for immune cell recruitment to solid tumours and has been manipulated to increase the anti-tumour response." (PMID 35205725, 2022). "Previous studies have found that the dysregulation of CXCR3 was negatively correlated with tumor invasion depth." (PMID 35571062, 2022). "Further studies to evaluate the different threshold levels of CXCL10 between tumor and immune cells to activate the CXCR3/pSrc pathway or to deliver tumor-selective CXCL10 inhibitors or CXCR3 inhibition will be considered." (PMID 36612121, 2022). "Gardner and their team recently shown that TIM-3 blockade promotes expression of CXCR3 chemokine ligands by tumor cDCs." (PMID 36479091, 2022). "With the elucidation of its mechanism of action, CXCR3 is expected to become a new indicator for evaluating the prognosis of patients with tumors and a new target for clinical tumor immunotherapy." (PMID 36479091, 2022). "CXCR3-dependent anti-tumor efficacy and upregulation of its ligands in mouse and human tumors were observed following PD-1/CTLA-4 checkpoint blockade." (PMID 36132332, 2022). "The expression of CCR7 is responsible for the recruitment of circulating NK cells to secondary lymphoid tissue, while high level of CXCR3 is detected on tumor-infiltrating NK cells." (PMID 35008589, 2021). "In a study on liver graft injury and tumor recurrence after liver transplantation, CXCL10/CXCR3 signaling upregulated at liver graft injury induced mobilization and recruitment of Tregs, which further promoted tumor recurrence after transplantation." (PMID 34504204, 2021).